STK11 (serine/threonine kinase 11)
Diseases named in the same sentence as STK11 in open-access papers (continued):
Sharing a sentence is not in itself a finding about the gene and the disease.
tumor (continued). "These non-mutational mechanisms should be considered in tumor characterization because such tumors could have growth and aggressiveness similar to STK11-mutant tumors." (PMID 34831355, 2021). "However, STK11 mutations were associated with a lack of PD-L1 expression in tumor cells, despite the presence of intermediate or high TMB, irrespective of KRAS status." (PMID 34831355, 2021). "The loss of STK11/LKB1 causes suppression of stimulator of interferon genes (STING), a reduced expression of type I interferon genes and chemokines that promote T-cell recruitment, and tumour cells appear to lack PD-L1 expression, which altogether can be attributed to immunotherapy resistance." (PMID 33116132, 2020). "STK11 gene inactivation either by mutational or non-mutational machinery is linked to an indolent immune microenvironment with lower Tumor-infiltrating lymphocyte (TILs; CD3+, CD4+, and CD8+ cells) and PD-L1 expression in spite of the existence of moderate to high TMB." (PMID 33194652, 2020). "However, those reported in the context of Peutz‐Jeghers syndrome are most likely driven by STK11 alterations and may fall within the spectrum of tumours currently designated as intratubular large cell hyalinising Sertoli cell neoplasia (see corresponding section below)." (PMID 41384702, 2026). "Conversely, the association between high PLK1 expression and an immunosuppressive tumor microenvironment, as demonstrated in our data, suggests that PLK1 inhibitors might synergize with immunotherapies in immune-“cold” subtypes, such as those with STK11 mutations." (PMID 41556056, 2026). "Compared with those in normal tissue, KEAP1, STK11, and CDKN2A were highly expressed in the tumor samples of NSCLC patients (P < 0.01)." (PMID 41491583, 2026). "The condition is caused by germline mutations in the Serine/Threonine Kinase 11/Liver Kinase B1 (STK11/LKB1) gene, a tumor suppressor involved in cell cycle regulation." (PMID 40371402, 2025). "Clinically, KRAS-mutant tumors with STK11/KEAP1 inactivation are known to be less responsive to immune checkpoint inhibitors and often exhibit a “cold” tumor immune microenvironment (low PD-L1, Programmed Death-Ligand 1, with low T-cell infiltration)." (PMID 40723270, 2025). "However, as KEAP1 mutations frequently co-occur with STK11 mutations in clinical samples, which is also known to modulate the tumor immune milieu, these clinical observations suggest that NRF2 may act collaboratively with STK11 to cause the lower-level immune cell infiltrations in the tumors." (PMID 41035689, 2025). "CircR-DENND2D down-regulates miR-130b-3p to promote STK11 expression, leading to enhancement of CD8+ T cells activity, inhibition of tumor immune escape, and reduction of anti-PD-1/PD-L1 inhibitor resistance in NSCLC." (PMID 40296912, 2025). "It is important to note that analysing fast disease progression cases in our research, both patients with STK11 and KEAP1 wild-type tumours had low TMB and harboured ERBB2 alterations (amplification and co-occurring alteration)." (PMID 40650126, 2025). "Among patients with both STK11 and KEAP1 wild-type tumours, a low TMB and alterations in the ERBB2 pathway were detected in 66.7% of cases." (PMID 40650126, 2025).
tumor (continued). "In contrast, among patients with both STK11 and KEAP1 wild-type tumours, low TMB and alterations in the ERBB2 pathway were detected in 2/3 of cases." (PMID 40650126, 2025). "Dual inactivation of STK11 and KRAS genes alters the tumor secretome, resulting in increased secretion of IL-6." (PMID 41051525, 2025). "Serine threonine kinase 11 (STK11), also known as LKB1, is a ubiquitously expressed and evolutionarily conserved serine/threonine kinase identified as a tumor suppressor." (PMID 39115053, 2025). "In a small number of cases, these genomic bottleneck events resulted in the derivation of PDX models with a different complement of driver alterations from the same tumor (seen in this study affecting CDKN2A, STK11 and MGA)." (PMID 38821942, 2024). "Moreover, some clinical researchers demonstrated a significant correlation between STK11 expression and PD-L1 expression in tumor tissues, often showing a lower expression of PD-L1 in patients with STK11mut, providing further evidence that STK11mut may indicate poor immunotherapeutic outcomes." (PMID 38632512, 2024). "Liver kinase B1 (LKB1), also referred to as serine/threonine (Ser/Thr) kinase 11 (STK11), is an important tumor-suppressor gene." (PMID 39063214, 2024). "Immunoblot analysis of the parental and engineered H1792 cell lines demonstrated only decreased STK11/LKB1 protein expression in the H1792ΔSTK11 tumor cells compared with H1792ΔGFP and parental H1792 tumor cells." (PMID 37092555, 2023). "Additionally, PI3K, AKT, and mammalian target of rapamycin (mTOR) inhibitors may serve as potential therapeutic options for patients with PIK3CA and PTEN mutations, whereas an mTOR inhibitor can be used as a therapeutic approach for targeting STK11- and FBXW7-deficient tumours." (PMID 38024139, 2023). "CSF1R, FGFR1, FLT3, and KDR are related to the tumor microenvironment, and ERBB4, STK11, PTEN, and NPM1 are related to proliferation-related factors." (PMID 36780540, 2023). "STK-11/LKB1 is a multifaceted protein with a critical role in cell regulation, energy sensing, and tumor suppression." (PMID 38003971, 2023). "Despite all average tumor volumes being statistically equivalent across cohorts and time points, there was a trend toward increasing tumor volumes when STK11/LKB1 was completely silenced." (PMID 37092555, 2023). "Subsequently, immunohistochemistry was used to detect the expression of STK11, Ki67, and CD1E in tumor tissues." (PMID 37506141, 2023). "Liver Kinase B1 (LKB1), also known as the serine-threonine kinase (STK) 11, is a tumor suppressor gene." (PMID 35896782, 2022).
tumor (continued). "STK11: the serine/threonine kinase 11 (STK11), also known as liver kinase B1 (LKB1), is a tumor suppressor gene." (PMID 36499345, 2022). "However, it is not clear whether the impact of STK11 mutations is predictive of poor response to ICIs specifically, or simply prognostic of aggressive tumor evolution." (PMID 35515125, 2022). "Serine/threonine kinase 11 (STK11) regulates cell polarity, growth and proliferation and DNA damage response and function as a tumor suppressor gene." (PMID 35163129, 2022). "Liver kinase B1 (LKB1), also known as STK11, is a ubiquitously expressed master serine/threonine kinase that has been demonstrated to have tumor suppressing activity." (PMID 34084284, 2021). "STK11 (serine/threonine kinase 11), also named LKB1 (liver kinase B1), is a tumor suppressor gene that regulates cellular metabolism/energy homeostasis, growth and polarity." (PMID 33658393, 2021). "Liver kinase B1 (LKB1), also known as serine/threonine kinase 11 (STK11), is a tumor suppressor and a conserved regulator of cellular energy metabolism in eukaryotic cells." (PMID 32640596, 2020). "EGFR and KRAS genes were classified as oncogenes and STK11, RB1 and MGA genes were classified as tumor suppressors." (PMID 32998690, 2020). "Recently, the tumor suppressor liver kinase B1 (LKB1), also known as serine/threonine kinase 11 (STK11), has gained attention for its dual role as a tumor suppressor and proto‐oncogene." (PMID 28700115, 2017). "The gene responsible for PJS is STK11 (serine-threonine-kinase 11), which codes for liver kinase B1 (LKB1), a tumor suppressor gene." (PMID 25694554, 2015).
tumor (continued). "Implantation of KP cells, or a "KPS" cell line lacking the Stk11 gene, led to rapid tumor growth and death of all host animals." (PMID 41676515, 2026). "Other somatic mutations associated with VTE independent of tumor type include KRAS, STK11, MET, KEAP1, CTNNB1, and CDKN2B." (PMID 39851266, 2025). "We demonstrated the transition of PTC to SCC, in which tumor cells carried none of the common driver mutations (e.g. BRAF or RAS), but showed biallelic inactivation of KEAP1, STK11, and RB1." (PMID 40600748, 2025). "Recently, STK11/LKB1 co-mutated with KRAS (KL subtype) were found to be resistant to anti-PD1 treatment due to the presence of a strong association between STK11/LKB1 genomic alterations and lack of PD-L1 expression on tumor cells." (PMID 39932765, 2025). "In contrast, variants in STK11, PMS2, MUTYH, and RB1 were primarily classified as VUS and did not demonstrate an apparent relationship with tumor aggressiveness." (PMID 41595443, 2025). "STK11 and KEAP1 mutations are also not reliable predictors of response to ICI therapy, given their association with a non-inflamed tumor microenvironment (TME) and frequent co-occurrence with mutations such as KRAS." (PMID 40535117, 2025). "On tumor tissues, we discovered the germline STK11 gene nonframeshift deletion on exotic 5 on Chr19." (PMID 40018404, 2025). "Additionally, a subset of patients with somatic STK11 and/or KEAP1 alterations, along with lower baseline circulating tumor DNA, also experienced this clinical benefit." (PMID 38611005, 2024). "Whole exome sequencing (WES) identified a KEAP1/STK11 co-mutation with loss of function for both genes, a MAP2K1 activation, and an ARID2 loss of function, as well as a low tumor mutational burden (TMB) with no actionable mutation (4.4 mut/Mb)." (PMID 39170614, 2024). "NSCLC patients with KRAS and STK11 co-mutations are also more likely to carry the mutations in KEAP1 and ATM genes and are predisposed to the development of a cold tumor (without immune cells in tumor microenvironment)." (PMID 37509393, 2023). "In our classification, RAG-1 is enriched in STK11/LKB1 mutants, suggesting that this tumour group could be refractory to immune checkpoint blockade (ICB)." (PMID 36163168, 2022). "No patients with an STK11 mutation achieved a partial response by RECIST criteria, and, in two of them, the surgical resection showed no MPR, and the third tumor was unresectable." (PMID 35681755, 2022). "Given the evidence that tumor cells are Lkb1-positive and strict EYFP expression in tumor ECs (identified by positive staining for vWF [vWF+]) in the lineage-tracking mice (Stk11ec (EYFP)−/−), we concluded a non-cell-autonomous effect of EC Stk11 deficiency on tumorigenesis or tumor suppression." (PMID 35115536, 2022). "The tumor tissue was positive for KRAS, STK11, and PDL1 < 24%." (PMID 34298855, 2021). "Donor of BKZ-8 did not reveal any therapeutic relevant mutation, while the tumor material of BKZ-9 donor showed mutations in the KRAS gene and in STK11." (PMID 33925297, 2021). "We also find that the STK11, CD14, and BRD7 genes in the manatee were also well conserved, suggesting that extant manatees may also have enhanced tumor suppression and an augmented stress response." (PMID 33513090, 2021).
tumor (continued). "Several studies showed that NB metastatic cells express distinctive features from primary tumor cells, including down-regulation of several tumor suppressor genes (i.e., SIRT6, BBC3/PUMA, STK11, CADM4 and GLTSCR2) and up-regulation of immunosuppressive molecules, such as calprotectin and HLA-G." (PMID 33921337, 2021). "Four tumor samples from stage II (early stage), and six and twenty-six HNC tumors classified as III and IV stages (advanced stages), respectively, were analyzed to quantify STK11 expression level." (PMID 32911741, 2020). "Co-occurring KEAP1 and phosphatase and tensin homolog (PTEN) inactivation represent an immunologically “cold” tumor while concurrent mutations in KEAP1 and STK11 leads to absence of pro-cancerogenic M2 macrophages." (PMID 33194652, 2020). "Also, PFS and OS were significantly shorter in patients with KRAS/STK11 co-mutant tumor than in those with KRAS mutant and STK11 wild type (KRASm/STK11wt) tumor (PFS: p < 0.001; OS: p = 0.0015)." (PMID 32365882, 2020). "To identify the potential effect of anti-tumor drugs, we used the GDSC database to attempt to identify potentially sensitive and selective drugs for patients with or without STK11 mutation." (PMID 33425731, 2020). "Together, these findings may support the importance of regulation of STK11 through post-transcriptional regulation in HNC and the possible contribution to the carcinogenesis process in this neoplasia." (PMID 32911741, 2020). "KRAS/STK11 NSCLC (25% of KRAS+ NSCLC) lacked tumor-infiltrating lymphocytes and expressed reduced levels of immune markers and PD-L1." (PMID 32560574, 2020). "In particularly, STK11 mutations, inactivated in 20 to 30% of adenocarcinomas, and often associated with KRAS mutations, are associated with non-inflamed tumor microenvironment in a murine model." (PMID 31172347, 2019). "Interestingly, in tumor S2, two driver genes, GATA2 and STK11, were located in the ancestor subclone, and STK11 also harbors neo‐epitope." (PMID 27998038, 2017). "We detected STK11 gene nonframeshift deletion in our GEA tumor." (PMID 40018404, 2025). "We detected the germline alterations STK11 gene non-frameshift deletion in our GEA tumor by WES." (PMID 40018404, 2025). "However, given metformin’s role as a regulator of metabolism, understanding how metformin affects the metabolism of STK11 mutant NSCLC, and whether this process is involved in promoting anti-tumor immunity remains unknown." (PMID 39308524, 2024). "Isogenic cell lines upon confirmation of STK11 knockout (by immunoblotting for the LKB1 protein) were implanted into the right flank of syngeneic recipient mice and cohorts of tumor-bearing mice were randomized to be treated with anti-PD-1 antibody or IgG control." (PMID 38291516, 2024).